IL18 (interleukin 18)
Diseases named in the same sentence as IL18 in open-access papers (continued):
Sharing a sentence is not in itself a finding about the gene and the disease.
heart failure (continued). "In heart failure, activation of the NLRP3 inflammatory mediates the release of pro-inflammatory mediators such as IL-1β and IL-18, considered significant contributors to myocardial fibrosis and cardiac dysfunction in heart failure." (PMID 39022620, 2024). "This study showed the increased secretion of IL-1β and IL-18 when DUOX1 was overexpressed in AC16 cells, suggesting that the caspase-1-dependent pyroptosis in heart failure was triggered by the upregulation of DUOX1." (PMID 38750444, 2024). "In previous studies, IL-18 was found to act via PI3K/PDK1/Akt/GATA4-induced cardiac hypertrophy and play an important role in cardiac remodeling and heart failure." (PMID 37551283, 2022). "Heart failure evokes inflammation, and TNF-α, IL-6, IL-18, and atrial natriuretic peptide (ANP) can be induced in pressure overload-induced heart failure." (PMID 33597865, 2020). "As expected, we found that caspase-1 overexpression aggravated the activation of IL-1β and IL-18 in Re-TAC 4W mice, recapitulating that HP attenuates cardiac hypertrophy and regresses heart failure through downregulation of the inflammatory cascade of caspase-1." (PMID 33842546, 2021). "The aim of this study is to assess the circulating level of interleukin (IL)-6 and IL-18 in patients with ischemic and idiopathic DCM who suffer from heart failure symptoms in order to determine the effects of two main etiologies of DCM on expression of these two interleukins." (PMID 31384408, 2019). "The role of IL18 in AMI has not been clearly defined but growing evidence supports an important role of IL18 in both AMI and heart failure." (PMID 35558073, 2022).
Crohn disease (41 papers, 2010 to 2026). A gastrointestinal disorder characterized by chronic inflammation involving all layers of the intestinal wall, noncaseating granulomas affecting the intestinal wall and regional lymph nodes, and transmural fibrosis. "This assertion was further strengthened in a study that found that Crohn’s disease patients resistant to anti-TNF therapy had genetically susceptible IL-18 SNP and high serum IL-18 level." (PMID 36032110, 2022). "In addition, IL-18 polymorphisms reducing IL-18 levels have been implicated in susceptibility to Crohn’s disease." (PMID 41480237, 2026). "In this way, it has been suggested that IL-18 polymorphisms known to reduce IL-18 mRNA and protein levels may be involved in the susceptibility to Crohn’s disease." (PMID 36313762, 2022). "IL-18 is a pro-inflammatory cytokine with stimulatory effects on both T helper-1 and T helper-2 cell responses that have been implied in Crohn’s disease and ulcerative colitis, respectively." (PMID 35838945, 2023). "IL-16 and IL-18 had a suggestive association with an increased risk of ulcerative colitis (UC), and CXCL10 had a suggestive association with an increased risk of Crohn’s disease (CD)." (PMID 37228614, 2023). "A phase II trial of a recombinant human IL-18-neutralizing antibody for treating moderate to severe Crohn's disease (CD) is currently under testing (ClinicalTrials.gov Identifier: NCT03681067)." (PMID 38031150, 2023). "Serum IL-18 concentration was considerably increased in patients with Crohn’s disease than healthy patients suggesting that infiltrated macrophages in the inflamed intestinal mucosa produced IL-18 which then potentially regulate intestinal mucosa lymphocytes." (PMID 36032110, 2022). "Increased IL-18 levels in serum and mucosal biopsies are correlated to Crohn’s disease and IL-18 upregulation is reported to be a feature of CD19,20." (PMID 35169117, 2022). "As such, concerns should be taken when the IL-18 blockade, which can suppress epithelial barrier function and T-cell-mediated host defence, is developed for treating mucosal inflammation such as Crohn’s disease." (PMID 35169117, 2022). "IL-18 levels in sera and colon mucosal biopsies are significantly elevated in patients with Crohn’s disease, and correlate with disease activity and inflammatory markers." (PMID 31428451, 2019). "Interleukin 18 (IL-18), a key immune regulator of intestinal homeostasis, was shown to be overexpressed in the human large intestine during both Crohn’s disease and in T. muris-infected mice." (PMID 27632204, 2016). "Two years later, IL-18 was demonstrated to be localized and increasingly expressed in intestinal mucosal cells of patients with Crohn's disease (CD)." (PMID 26355424, 2015). "IL-18 is found in affected intestinal lesions from Crohn’s disease patients as a mature protein but the IL-18 precursor form is present in uninvolved intestinal tissues." (PMID 24115947, 2013). "IL‐18 is involved in developing IBDs, such as ulcerative colitis and Crohn's disease." (PMID 39188114, 2024). "Although IL-18 has a protective role in the early phase of inflammation, increased levels of this cytokine were observed in intestinal pathological conditions, such as Crohn’s disease." (PMID 37446274, 2023). "Ulcerative colitis and Crohn’s disease differ concerning the IL-18 involvement." (PMID 36010364, 2022). "Furthermore, IL-18 is a critical pro-inflammatory cytokine secreted by IECs of colons from Crohn’s disease patients, involved in an inflammatory caspase-1-dependent manner." (PMID 36120344, 2022). "High concentration of IL-1β and IL-18 cytokines is observed in patients with Crohn’s disease." (PMID 34630405, 2021). "There appears to be a role for blocking IL-18 in Crohn’s disease." (PMID 24115947, 2013). "IL-18 vaccine may provide a potential therapeutic approach in the treatment of Crohn’s disease." (PMID 31428451, 2019).
Crohn disease (continued). "Genetic studies have identified candidate loci for Crohn's disease susceptibility among autophagy genes, while experiments in murine macrophages from ATG16L1 deficient mice have shown that disruption of autophagy increases processing of IL-1β and IL-18 through an inflammasome-dependent manner." (PMID 21490934, 2011). "Despite these limitations, the results of first study were clear in showing that circulating cells from patients with Crohn’s disease exhibited significantly higher mean NLRC4-induced IL-1β and IL-18 responses than cells from control individuals." (PMID 41246319, 2025). "In another study in a murine model of Crohn's disease, UCN could control inflammatory diseases by inhibiting a wide range of inflammatory cytokines such as TNF-α, IFN‐γ, IL-6, IL-1α, IL-1β, IL-12, IL-18, IL-17, and IL-15." (PMID 35419072, 2022). "IL-18 induces only Crohn’s disease, but not in all patients, enhancing NK cell cytotoxicity and stimulating Th1 responses." (PMID 36010364, 2022). "IL-18 levels are comparable in our dataset between the control cohort and ME/CFS patients (p = 0.8, q = 1), which separates this cohort from Crohn’s disease patients, where both IL-18 and IL-18 BPa are higher in patients compared to healthy controls." (PMID 33572894, 2021). "The production of IL-1β and IL-18 is increased in the absence of functional ATG16L1 in a mouse model of Crohn’s disease." (PMID 25409294, 2014).
ischemic stroke (41 papers, 2013 to 2026). A stroke disorder caused by obstruction of blood flow to the brain, due to thrombotic (local blood clot formation) or embolic (due to a blood clot or other material traveling from another site) event. "The NLRP3 inflammasome regulates the release of pro-inflammatory factors IL-1β and IL-18, one of the critical steps leading to neuronal cell death associated with ischemic stroke." (PMID 36232980, 2022). "Strokes caused by an ischemic stroke can induce the release of inflammatory cytokines, including IL-1β and IL-18." (PMID 36105479, 2022). "Previous results regarding the association between IL-18 level and ischemic stroke have been inconsistent." (PMID 31525735, 2019). "In conclusion, our results were consistent with other studies demonstrating that high IL-18 level is strongly linked to ischemic stroke." (PMID 31525735, 2019). "IL-18 gene −607 C/A and −137 G/C variants were compared between subjects having had ischemic stroke and healthy controls in a Han Chinese cohort." (PMID 29485097, 2018). "MCC950, a potent inhibitor of the NLRP3 inflammasome, significantly reduces levels of IL-1β and IL-18 in brain tissue and attenuates neutrophil infiltration in mouse models of ischemic stroke." (PMID 41451205, 2025). "The NLRP3 inflammasome is a multiprotein complex that becomes activated following ischemic stroke, promoting the maturation and release of IL-1β and IL-18, thereby exacerbating neuroinflammation." (PMID 41451205, 2025). "IL-1β and IL-18 antagonists have been shown to inhibit the NLRP3 inflammasome consequently attenuating the adverse effects of ischemic stroke." (PMID 41542272, 2024). "Since the inflammatory response is involved in the pathological process of ischemic stroke, we used ELISA to observe the alteration of IL-1β and IL-18 after ischemic stroke and if exercise preconditioning can modulate their excretion." (PMID 36262547, 2022). "The mRNA expression levels of NLRP3, SIRT1, and IL-18 on an animal model of ischemic stroke with CPSP were measured by qRT-PCR to validate the data mining findings from GEO." (PMID 36059399, 2022). "IL-18 is secreted by microglia and monocytes/macrophages in the infarcted cortex after ischemic stroke rodents and humans." (PMID 32365331, 2020). "IL-18 level in patients with severe ischemic stroke was higher than those in patients with moderate ischemic stroke (SMD =3.33, 95% CI = 1.37 ~ 5.29, p = 0.001)." (PMID 31525735, 2019). "High levels of IL-18 have been found in unstable carotid plaques, leading to high IL-18 level after ischemic stroke." (PMID 31525735, 2019). "The results of our study have revealed a strong link between higher levels of IL-18 and the development and severity of ischemic stroke." (PMID 31525735, 2019). "IL-18 level in patients with moderate ischemic stroke was higher than those in patients with mild ischemic stroke (SMD =1.79, 95% CI = 0.90 ~ 2.68, p< 0.001)." (PMID 31525735, 2019). "The combined IL-18 AA/MMP-9 CT/TT genotypes associated with an increase in risk of composite endpoints (OR = 1.87; 95% CI = 1.13–3.11, p = 0.015, adjusted) and ischemic stroke (OR = 2.54; 95% CI = 1.07–6.00, p = 0.034, adjusted)." (PMID 24040261, 2013). "Furthermore, edaravone dexborneol exerted neuroprotective effect by inhibiting NF-κB/NLRP3/GSDMD signaling pathway and inflammatory factors (IL-1β and IL-18) in experimental ischemic stroke." (PMID 38902691, 2024). "The emerging role of IL-18 in CNS pathologies, as ischaemic stroke and inflammation-driven neurodegeneration has been supported by multiple studies and Casp8 was reported in association with neuron-specific apoptotic processes and as a major pathogenetic factor in Alzheimer’s disease." (PMID 38105266, 2023). "In the current study, we discovered that IPC could significantly inhibit the expression of NLRP3 inflammasome components and partially reduce the level of IL-1β and IL-18 at 6 h and 24 h following ischemic stroke, especially at the 24 h time point." (PMID 37371374, 2023).
ischemic stroke (continued). "Hence, agents that inhibits NLRP3 inflammasome exert a neuroprotective effect on ischemic stroke and post-stroke depression via suppressing the expression of IL-18." (PMID 35173738, 2022). "By regulating IL-1β and IL-18 secretion, they play a role in ischemic stroke." (PMID 36105479, 2022). "NOX inhibitor apocynin and nicotinamide adenine dinucleotide phosphate (NADPH) could inhibit the level of NLRP3, ASC, caspase-1, IL-1β and IL-18 in the cortex, improve the neurological functions, and decrease the infarct volume in ischemic stroke mouse model." (PMID 32581721, 2020). "NLRP3 inflammasomes can regulate glial and neuronal cell death in ischemic stroke via enhancing generation and secretion of the pro-inflammatory cytokines including IL-1β and IL-18 and through pleiotropic impacts of cleaved-caspase-1 in regulating neuronal cell apoptosis." (PMID 32581721, 2020). "As the first identified inflammasome in cerebral ischemic injury, NLRP1 inflammasome could activate precursor caspase-1 to produce both mature IL-1β and IL-18 to mediate neurocytes death after ischemic stroke." (PMID 31416289, 2019). "In addition, upregulated levels of IL-18 are believed to play a crucial role in ischemic stroke attacks." (PMID 31525735, 2019). "Additionally, IL-18 level was higher in patients with severe ischemic stroke than in patients with moderate ischemic stroke, and IL-18 level was higher in patients with moderate ischemic stroke than in patients with mild ischemic stroke." (PMID 31525735, 2019). "Moreover, circulating IL-18 levels from blood drawn 48 h after ischemic stroke was a major predictor of 90-day major adverse clinical outcomes in this cohort." (PMID 27905989, 2016). "Previous reports showed that JQ1-treated animals exhibit a marked reduction in the expression of pro-inflammatory mediators IL-1β, IL-6, IL-17, IL-18, and TNF-α in the brain in rodent ischemic stroke models." (PMID 35761277, 2022). "Accordingly, ischemic stroke was found to significantly increase the levels of cleaved caspase-1, ASC, NLRP3, cleaved GSDMD, IL-1β, and IL-18." (PMID 33584203, 2020). "Besides, light-emitting diode (LED) treatment could decrease neuroinflammatory reactions and brain damage after ischemic stroke via reducing cell death, decreasing IL-1β and IL-18, and inhibiting NLRP3 inflammasome, MAPK signaling, TLR-2 levels and NF-κB activation." (PMID 32581721, 2020). "LED therapy also downregulated the expression of proinflammatory cytokines IL-18 and IL-1β and attenuated the NLRP3 inflammasome in an ischemic stroke model." (PMID 31287006, 2019). "In this study, we demonstrated that the ischemic stroke-induced activation of NLRP3 was significantly reduced by MFSCE, as so were the downstream targets of cleaved caspase-1 and caspase-11, mature IL-1β, and IL-18." (PMID 35454994, 2022). "Acupuncture may inhibit CPSP in an animal model of ischemic stroke by upregulating SIRT1 expression levels, inhibition of the activation of the inflammasome, and downregulating IL-18 expression levels." (PMID 36059399, 2022). "Studies have shown that increased IL-18 level contributed to the development of ischemic stroke, and nonspecific inflammatory factors, such as hypersensitivity C-reactive protein and ESR, are elevated in the high RDW group." (PMID 32445553, 2020). "QRT-PCR results on animal models of CPSP ischemic stroke showed that the expression levels of SIRT1 were downregulated, the activation of the NLRP3 inflammasome was upregulated, and the expression levels of IL-18 were upregulated in the brain tissues of the surrounding area of the injury." (PMID 36059399, 2022). "Levels of IL-18 were not significantly elevated in patients with ischemic stroke." (PMID 24040261, 2013).
atopic dermatitis (40 papers, 2009 to 2025). "IL-18 is a proinflammatory IL-1 family cytokine that is increasingly associated with atopic dermatitis." (PMID 40869264, 2025). "High blood concentrations of IL-18 are also found in patients with allergic diseases, including bronchial asthma, atopic dermatitis, inflammatory bowel disease, and the X-linked inhibitor of apoptosis (XIAP) deficiency." (PMID 30992532, 2019). "IL18, on the other hand, can stimulate both Th1 and Th2 responses, and appears to be causally involved in a different type of atopic dermatitis." (PMID 27431613, 2016). "More recently, IL18 knockout mice were shown to be resistant to infection-associated atopic dermatitis, in a mouse model generated by perturbing the stratum corneum with detergent prior to topical application of S. aureus protein A." (PMID 27431613, 2016). "IL-18 has been associated with autoimmune diseases or inflammatory disorders, bronchial asthma, atopic dermatitis, RA, psoriasis, multiple sclerosis, and type I diabetes." (PMID 22876248, 2012). "In addition, a recent report indicates that IL-18 drives secretion of pathogenic cytokines from Th2 cells in atopic dermatitis, with IL-9 upregulating the IL-18R on Th2 cells." (PMID 40489556, 2025). "Consequently, IL-37 is linked to IL-18, which plays a role in the pathogenesis of atopic dermatitis (AD), consistent with our studies." (PMID 38067193, 2023). "Our meta-analysis suggests that IL-18 −607C/A and −137G/C polymorphisms may be protective factors for the risk of allergic asthma and allergic dermatitis, respectively." (PMID 24995282, 2014). "IL-18, traditionally thought of as a Th1-promoting cytokine, has been implicated in the development of atopic dermatitis; transgenic mice expressing either human caspase-1 or IL-18 in keratinocytes develop spontaneous atopic dermatitis-like lesions with elevated mast cell activity." (PMID 24409181, 2013). "IL-18 was reported to be the most significantly elevated biomarker also in the skin of Atopic Dermatitis (AD) patients and correlated with disease severity (Rusiñol & Puig, 2024)." (PMID 39769266, 2024). "Increased concentrations of IL‐4, IL‐12, IL‐13 and IL‐18 have been found in humans with atopic dermatitis." (PMID 38648253, 2024). "The role of IL-18 in S. aureus infection is not yet fully understood, but it was shown in an atopic dermatitis (AD) mouse model that S. aureus increases the epidermal IL-18 production that was dependent on the activation of the NLRP3 inflammasome." (PMID 38571946, 2024). "An increase of serum IL18 has also been observed in human patients with atopic dermatitis and it has been suggested that IL18 can serve as a biomarker of disease severity." (PMID 32687504, 2020). "In the skin, activation of IL-18 has been identified as important in other autoimmune and inflammatory skin diseases such as vitiligo, atopic dermatitis, and alopecia areata." (PMID 32644977, 2020). "IL18 induces an increase of IgE in mice, and increased concentration of serum IL18 has been reported in human patients with atopic dermatitis." (PMID 32687504, 2020). "It has been noticed that IL-18 contributes to the spontaneous development of atopic dermatitis-like inflammatory skin lesion and skews, the invariant NKT-cell population via autoreactive activation in AE." (PMID 28839348, 2017). "In NC/Nga atopic dermatitis mouse model, IL-18 and mast cell had been shown to be important inflammation induced by Staphylococcus aureus." (PMID 26690141, 2015). "Higher serum levels of IL-18 have previously been identified in atopic dermatitis and asthmatic subjects." (PMID 24490166, 2013). "The obtained data visibly demonstrate that IgE, IL-18, and IL-12 could be useful in estimating atopic dermatitis activity, and could be helpful in forecasting the advance of the disease." (PMID 38672221, 2024).